UCHL1 (ubiquitin C-terminal hydrolase L1)
Diseases named in the same sentence as UCHL1 in open-access papers (continued):
Sharing a sentence is not in itself a finding about the gene and the disease.
cancer (continued). "Our clonogenic cell survival assays and the quantitative analysis of metabolite levels collectively demonstrated that the UCHL1-mediated radioresistance was at least in part dependent on the antioxidant property of cancer cells elicited by HIF-1." (PMID 28761052, 2017). "Of note, expression of NUPR1 (a transcription factor involved in progression of liver and other cancers) was about 8-fold increased in our UCHL1 knockdown (p = 1.20x10-8)." (PMID 28472177, 2017). "Based on these findings, our study provides an insight into a novel strategy targeting G6pdx and HIF-1α to overcome the UCHL1-dependent radioresistance of cancer cells." (PMID 28761052, 2017). "All of these results strongly suggest that the aberrant overexpression of UCHL1 induces the antioxidant and radioresistant properties of cancer cells in a HIF-1- and G6pdx-mediated PPP-dependent manner." (PMID 28761052, 2017). "Pgp-9.5 (ubiquitin COOH-terminal esterase L1 or UCHL-1) is an ubiquitin COOH terminal hydrolase that is widely expressed in different type of cancer cells." (PMID 27473871, 2016). "The number of metastatic colonies 10 days after the intravenous transplantation of EMT6/EF-Luc/EV and EMT6/EF-Luc/UCHL1 cells also revealed that LDN57444 had an antimetastatic effect on UCHL1-expressing cancer cells." (PMID 25615526, 2015). "UCHL1 is also known as PGP9.5, a well-established marker for diagnosis and prognosis of a variety of cancers." (PMID 25605410, 2015). "Our results indicated that the aberrant expression of UCHL1 in cancer cells abrogated the VHL-mediated ubiquitination of HIF-1α, which led to the stabilization of HIF-1α and subsequent activation of HIF-1." (PMID 25615526, 2015). "Here the authors show that upregulation of Ubiquitin C-terminal hydrolase-L1 in human cancers promotes metastasis and correlates with poor prognosis because of its role in opposing ubiquitin-mediated degradation of HIF-1." (PMID 25615526, 2015). "In agreement with a previous report that UCHL1 can enter the nucleus of cancer cells, signals of tUCHL1 were detected by immunohistochemistry and immunofluorescence in the nucleus of toad oocytes at different developmental stages." (PMID 24194953, 2013). "This hypermethylation is correlated with low UCHL1 transcripts and protein levels in cancer compared to adjacent benign prostate epithelium." (PMID 21999842, 2011). "Our proteomic analysis of prostate tissue samples highlighted significant downregulation of UCHL1 in cancer compared to the surrounding benign tissue." (PMID 21999842, 2011). "At least 50 genes in our list are already known to be regulated by DNA methylation, such as those encoding cancer antigens (a set of MAGE and GAGE), H19, S100A4, IGFBP4, UCHL1, COL1A2, CLU, FN1, and TGFBI." (PMID 19234609, 2009). "Using different technologies UCHL1 has been identified as a frequently silenced gene in a cancer-specific manner, in particular in pancreatic, gastric, colon, ovarian, head neck squamous cell and hepatocellular carcinoma." (PMID 19857250, 2009). "Furthermore, UCHL1 has garnered attention across a multitude of cancer subtypes as it has the ability to be targeted through small molecule inhibition." (PMID 40078282, 2025). "While to the best of our knowledge, we are the first to report efficacy of small molecule UCHL1 inhibition specifically in chemoresistant HGSOC cells, there have been a number of studies in cancer that have described UCHL1’s complex role in both chemo- and drug-resistance." (PMID 40078282, 2025). "Interestingly, the function of UCHL1 in cancer has been heavily debated as numerous studies, even within the same cancer subtype has shown that UCHL1 can operate both as a suppressor and promoter of tumorigenesis." (PMID 40078282, 2025). "The role of UCHL1 in different types of cancer remains controversial." (PMID 40141757, 2025). "Recently, there has been an explosion of research elucidating the role of UCHL1 in cancer." (PMID 40078282, 2025).
cancer (continued). "Our findings reveal a critical pathway through which UCHL1-mediated deubiquitination sustains Twist1 stability, revealing a novel posttranslational regulatory axis involved in cancer metastasis and progression and highlighting promising therapeutic targets for metastatic NSCLC." (PMID 41469388, 2025). "UCHL1 is upregulated in Ov-CCA tissue samples and may be linked to hypomethylation in the promoter region and potential induction of UCHL1 expression through cancer-induced DNA repair mechanisms." (PMID 39236081, 2024). "UCHL1 expression was negatively correlated with most cancers, except for brain-related gliomas, which may be attributed to its absence in most tissues." (PMID 39034372, 2024). "We found that UCHL1 and SNRNP200 are significantly upregulated, and PAK4 is downregulated in high-grade CCRCC, and all are involved in critical cellular pathways linked to cancer progression and poor clinical outcomes." (PMID 39199615, 2024). "In addition to LRRK2, several other genes, e.g., α-synuclein, PTEN-induced kinase 1 (PINK1), F-box protein 7 (FBXO7), and ubiquitin C-terminal hydrolase L1 (UCHL1) show altered expression in cancer patients." (PMID 38612708, 2024). "UCHL3, the closest homologue of UCHL1, has an expression pattern similar to UCHL1 in cancers." (PMID 39034372, 2024). "UCHL1, a member of the ubiquitin carboxy-terminal hydrolase family, showed variable expression across different tissues and was notably involved in the Akt signaling pathway, which plays a critical role in cellular survival in various cancers." (PMID 39199615, 2024). "Whether UCHL1 is an oncogene or tumor suppressor in various cancer types remains a subject of debate, but several studies have reported that tumorigenesis is linked to the high expression of UCHL1." (PMID 38727276, 2024). "Based on complementary mechanisms of action, the combination of radiotherapy and certain DNA-damaging drugs or AKT- and PARP-inhibition might be beneficial for patients with UCHL1-related cancers." (PMID 36980544, 2023). "Again, UCHL1-related cancer cell lines had a significantly higher UCHL1 expression as compared to other cell lines, and we could also confirm significant differences in the UCHL1-related 497-gene set." (PMID 36980544, 2023). "Insights from this study might support further prospective (pre-) clinical studies investigating UCHL1-related cancers." (PMID 36980544, 2023). "However, as studies progressed, UCHL1 was found to be highly expressed in various cancers originating from different tissues, including the brain, lung, breast, kidney, colon and pancreas, and prostate." (PMID 36218038, 2023). "In summary, our study elucidated a novel molecularly-defined subgroup of UCHL1-related cancers across solid tumor entities, which is characterized by a higher genomic instability and increased sensitivity to radiotherapy or genotoxic agents as potential treatment vulnerabilities." (PMID 36980544, 2023). "Moreover, UCHL1-related cancers of the TCGA-PanCancer cohort shared an increased fraction of altered genome, indicating an overall genomic instability with similar hot spot regions as for TCGA-HNSC." (PMID 36980544, 2023). "Furthermore, the development of a classification model facilitates further investigation of UCHL1-related cancers and their specific vulnerabilities in pre-clinical models and future clinical trials." (PMID 36980544, 2023). "Additionally, the expression of UCHL1 in these cancers often correlates with increased metastatic behaviour, resulting in poor prognosis and prompting human cancer pathogenesis and progression." (PMID 37246623, 2023). "Limited PI3K-AKT signaling might render UCHL1-related cancer cells more sensitive for AKT inhibitors, but also genotoxic drugs or radiotherapy." (PMID 36980544, 2023).
cancer (continued). "As UCHL1 is frequently repressed by aberrant DNA methylation in a range of carcinomas, we wondered whether specific DNA methylation might result in efficient and sustained downregulation of UCHL1, as reported for other genes." (PMID 38016026, 2023). "We summarise reports of the first UCHL1 inhibitors and activity-based probes (ABPs) to delineate UCHL1-driven oncogenic mechanisms, and assist in the validation of this potential therapeutic target in cancer." (PMID 34497382, 2022). "In addition, the expression of UCHL1 was shown to be dysregulated in various tumor entities including pancreatic cancer, colorectal cancer, and breast cancer, where it can promote cancer invasion and metastasis." (PMID 36216817, 2022). "UCHL1 plays a vital role in anti-apoptosis, cancer cell invasion, migration and proliferation." (PMID 36233276, 2022). "Moreover, neurodegeneration, cancer, and fibrosis are closely related to the disorder of UCHL1 expression." (PMID 35546675, 2022). "Moreover, Uchl1 promotes H2O2 production by upregulating NADPH oxidase 4 (NOX4) activity through deubiquitination in the migration process of cancer cells, as well as in angiogenesis." (PMID 33967677, 2021). "UCHL1 suppresses diverse types of cancer by enhancing intrinsic apoptosis." (PMID 33919439, 2021). "In some cancers, the expression of UCHL1 is silenced through epigenetic regulation." (PMID 33919439, 2021). "UCHL1 promotes cancer cell apoptosis through diverse molecular pathways." (PMID 33919439, 2021). "Finally, the probes were shown to engage UCHL1 selectively in two different cancer relevant cells lines." (PMID 33668938, 2021). "Additionally, expression of UCHL1 in these cancers often correlates with increased metastatic behavior and poor patient prognosis." (PMID 33668938, 2021). "In line with those previous studies, our results also suggested that PSMD2 and UCHL1 may have therapeutic potential as targets against cancer." (PMID 34398824, 2021). "Therefore, there is a dual action of UCHL1 in a variety of diseases, including kidney diseases, neurodegenerative diseases and cancers, with UCHL1 affecting cellular proliferation, cell cycle, migration and invasion." (PMID 32606430, 2020). "Since UCHL1 affects the protein stability of target proteins in other cancer types by deubiquitination, we sought to determine whether UCHL1 directly affected the protein stability of cyclin B1." (PMID 31906456, 2020). "UCHL1 was indicated as a tumor suppressor gene, and its methylation might be a prognostic markers in several cancers." (PMID 31390840, 2019). "Moreover, silencing the HIF-1α gene completely abrogated the UCHL1-mediated radioresistance of cancer cells." (PMID 28761052, 2017). "Additionally, Pgp-9.5 (ubiquitin COOH-terminal esterase L1 or UCHL-1) is an ubiquitin COOH terminal hydrolase that is widely expressed in different type of cancer cells." (PMID 27473871, 2016). "UCHL1 has been identified as a cancer-specific methylated gene, and silenced by promoter methylation in multiple tumors including nasopharyngeal (NPC), esophageal squamous cell (ESCC), gastric, hepatocellular (HCC), colorectal, renal cell, and ovarian carcinomas." (PMID 22279545, 2012). "Mutations in the UCHL1 gene have been shown to be associated with Parkinson's disease rather than cancer, for which differential expression appears to be more common." (PMID 21999842, 2011). "However, UCHL1 has also been found in cells of the human diffuse neuroendocrine system and is expressed is several forms of cancer." (PMID 20302621, 2010). "However, as a deubiquitinating enzyme, UCHL1 may be involved in various pro-cancer pathways by stabilizing multiple substrates." (PMID 38468288, 2024). "In addition, UCHL1 overexpression promotes cancer cell migration and metastasis in NEPC and SCLC." (PMID 39372390, 2024).
cancer (continued). "As a critical component of the proteasome targeting the ubiquitin-dependent protein degradation pathway, UCHL1 is involved in key cellular functions such as proliferation, cell cycling, apoptosis, and intracellular signaling, all of which are often disrupted in cancer." (PMID 39199615, 2024). "Thus, this study might leverage basic and translational research on UCHL1-related cancers, contributing to clinical implications improving targeted treatment options for patients with UCHL1-related tumors." (PMID 36980544, 2023). "In addition, the list of confirmed compounds was enriched for AKT inhibitors (GSK2110183, GDC-0068, AZD5363), indicating that survival of UCHL1-related cancer cells depends at least in part on PI3K/AKT pathway activity, which appears to be lower as compared to other cancer cells." (PMID 36980544, 2023). "It was found that UCHL1 could distinguish cancer tissue from normal tissue." (PMID 35546675, 2022). "Similarly, IMP-1710 could be employed as a tool to study UCHL1-mediated TGF-β signaling in non-cancer contexts, such as cardiac remodeling." (PMID 34497382, 2022). "UCHL1 could either positively or negatively regulate cell proliferation of cancer cells." (PMID 30359286, 2018). "Therefore, DUB enzymes found to be deregulated in cancer, such UCHL1, may give rise to alternative cancer therapies as upstream regulators of “undruggable” oncoproteins." (PMID 28472177, 2017). "Within the list of top differentially expressed genes, in the UCHL1 KDs we found downregulation of the Wnt targets POSTN, SP7, and DLL1, of the transporter ABCA4, of the homeobox gene DLX4, and of genes recently linked to cancer progression ACTA2, AQ4, GRAP2, and ALK." (PMID 28472177, 2017). "Thus, we determined the cellular expression of UCHL1 in the prostate benign and cancer cell lines." (PMID 29126443, 2017). "UCHL1, an essential member of the proteasome targeting ubiquitin-dependent protein degradation pathway plays an important role in distinct cellular processes such as cell proliferation, cell cycle, apoptosis and intracellular signalling, which are often disturbed in cancers." (PMID 19857250, 2009). "Ubiquitin carboxyl terminal hydrolase L1 (UCHL1) belongs to the deubiquitinase (DUB) family of enzymes and is expired at high levels in various cancer types." (PMID 38706893, 2024). "UCHL1 is notably expressed in NEPC and SCLC, promotes cell growth in NEPC (NCI‐H660), NE‐like (DU145), and SCLC (NCI‐H82) cancer cell line, and upregulates NE signatures in CRPC‐adeno (22RV1) cell line in vitro." (PMID 39372390, 2024). "Sixty percent of the tumors analyzed expressed high levels of Vimentin and PGP9.5 [also known as Ubiquitin C-terminal hydrolase L1 (UCHL1)], suggesting the presence of cancer cells undergoing EMT." (PMID 38067168, 2023). "Surprisingly, we found that many cancer cells from P11 not only coexpressed NKX2-1 and TP63 but also showed high expression of CHGB and UCHL1, which are markers of neuroendocrine cells." (PMID 35962452, 2022). "UCHL1, also called PGP9.5, controls intracellular ubiquitin levels and is related to tumorigenesis in various cancer types." (PMID 36497313, 2022). "Ubiquitin C-terminal hydrolase L1 (UCHL1), which is a deubiquitinating enzyme, is known to play a role in chemoresistance in cancers." (PMID 33718207, 2021). "UCHL1, as a DUB, which promotes targeted protein stabilization, is reported that it is overexpressed in many organs and it has a major role in cancer treatment." (PMID 32801299, 2020). "In vitro colony formation assays demonstrated that the forced expression of UCHL1 significantly increased GSH levels and subsequently induced the radioresistance of cancer cells." (PMID 30634433, 2019). "Thus, the UCHL1-KD associated transcriptome may be able to uncover cancer associated genes, but also additional genes not involved in cancer per se but rather be considered within the context of neuroprotective functions associated with UCHL1." (PMID 28472177, 2017).
cancer (continued). "Further investigation is needed to fully understand the downstream effectors of the UCHL1-HIF-1 axis, which play critical roles in increasing the radioresistance of cancer cells." (PMID 28761052, 2017). "Notably, this anti-cancer effect was mediated through CIP2A deubiquitination, highlighting UCHL1 as a potential therapeutic target for future clinical investigation in GC." (PMID 41155583, 2025). "Given the critical roles of TSPAN8, UCHL1, and MYC in key biological processes in aggressive cancers like SCLC, targeting these molecules may offer valuable therapeutic potential." (PMID 40428124, 2025). "Based on these data, it is proposed that RG6016 may modulate the HIF-1α pathway via LSD1, UCHL1, and MYC in aggressive cancers such as SCLC, thereby influencing key processes like hypoxia response, metastasis, and neuroendocrine differentiation." (PMID 40428124, 2025). "UCHL1, a member of the UCH class of deubiquitinases (DUBs), has highlighted the importance of promoter region hypermethylation as a mechanism for gene inactivation in cancer." (PMID 39236081, 2024). "This suggests that UCHL1, SNRNP200, and PAK4 could serve as valuable prognostic markers, offering new insights into the progression and prognosis of this aggressive cancer subtype." (PMID 39199615, 2024). "However, selective and potent small-molecule UCHL1 inhibitors have been disclosed only very recently, alongside chemical biology approaches to detect regulated UHCL1 activity in cancer cells." (PMID 34497382, 2022). "The MethHC database showed that the UCHL1 promoter is also hypermethylated in these cancers, and there are strong negative correlations between UCHL1 promoter methylation and mRNA expression in these cancers as well." (PMID 32120844, 2020). "Chronic inflammation with the alteration of the COX2 enzyme and of the ubiquitin proteasome system seems to play a central role in this link, and in particular, the ubiquitin carboxyl-terminal hydrolase isozyme L1 (UCHL1) is among the genes involved in both PD and cancer pathogenesis." (PMID 31191748, 2019). "Here, we show that Ubiquitin C-terminal hydrolase-L1 (UCHL1), which we previously identified as a novel HIF-1 activator, increased the radioresistance of cancer cells by producing an antioxidant, reduced glutathione (GSH), through HIF-1-mediated metabolic reprogramming." (PMID 28761052, 2017). "DUBs are critical key players in diverse processes such as (i) spermatogenesis (e.g. USP2, USP8, USP9y, USP14, USP26, Uchl-1, Uchl-3 and CYLD), (ii) cancer biology (e.g. USP7, USP10 and USP11), and (iii) stemness and differentiation (e.g. USP7, USP9x, USP22, USP44 and Psmd14)." (PMID 28659380, 2017). "Several candidate gene products (UCHL1, SNAT1, and EGR1) were selected to investigate whether PRR11 influences their expression in HC cancer cells." (PMID 25971332, 2015). "Therefore, a more comprehensive set of experiments are required to explore the effect of UCHL1 inhibition in both type of cell lines (ER− and TNBC) to validate whether these roles of UCHL1 depend on cancer context." (PMID 34497382, 2022). "However, a relationship between UCHL1 and p27Kip expression in cancers including RCC has also not yet been determined." (PMID 19857250, 2009). "Our data also suggest that the higher sensitivity to genotoxic stress is, at least in part, cancer-cell-intrinsic as UCHL1-related cell lines from CCLE exhibit a lower integral survival after ionizing irradiation compared to their counterpart without a UCHL1-related phenotype." (PMID 36980544, 2023). "Based on this screening we tested whether the lack of UCHL1 expression in RCC cell lines could be attributed to aberrant CpG islet methylation within its promoter region, which represents a common mechanism of gene silencing in various human cancers." (PMID 19857250, 2009).